TGFBR1 (transforming growth factor beta receptor 1)
Diseases named in the same sentence as TGFBR1 in open-access papers (continued):
Sharing a sentence is not in itself a finding about the gene and the disease.
osteosarcoma (8 papers, 2010 to 2025). A usually aggressive malignant bone-forming mesenchymal neoplasm, predominantly affecting adolescents and young adults. "The decreased risk of distant metastasis of osteosarcoma in TGFBR1*6A variants suggests that TGF-β signaling is involved in the metastasis of osteosarcoma." (PMID 20429896, 2010). "This case-control study shows a significant statistical association between TGFBR1*6A variant and osteosarcoma in a Chinese population." (PMID 20429896, 2010). "Three models - dominant, additive and recessive - were used to analyze the contribution of the TGFBR1*6A variant to osteosarcoma susceptibility." (PMID 20429896, 2010). "TGFBR1*6A, a dominant polymorphism of TGFBR1, is associated with increased susceptibility and metastasis spread of osteosarcoma." (PMID 20429896, 2010). "The TGFBR1*6A variant is also significantly associated with the distant metastasis of osteosarcoma in the Chinese population studied." (PMID 20429896, 2010). "Although the functional variants of TGFBR1*6A increases susceptibility to osteosarcoma, it decreases the probability of metastasis." (PMID 20429896, 2010). "When the data were analyzed with the dominant, additive and recessive models, there were significant increases in TGFBR1*6A variants in osteosarcoma cases compared to control in all of the (P < 0.01)." (PMID 20429896, 2010). "There were significant increases in the TGFBR1*6A variants in osteosarcoma cases compared to control in all 3 models." (PMID 20429896, 2010). "Several studies have reported that common genetic variations were preliminarily associated with the occurrence of osteosarcoma in some biological pathways, such as TGFBR1*6A, which is a common mutation of TGF-β receptor 1 and was reported to be associated with the distant metastasis of osteosarcoma." (PMID 29720180, 2018). "Our study firstly demonstrates the significant association between TGFBR1*6A and osteosarcoma, which may be due to the important role of TGF-β signaling in the control of osteosarcoma." (PMID 20429896, 2010). "The genetic variant of TGFBR1*6A could represent a functional modification in the TGF-β signaling pathway in osteosarcoma." (PMID 20429896, 2010). "TGFBR1*6A is associated with an increased cancer risk, but the association of this polymorphism with osteosarcoma remains unknown." (PMID 20429896, 2010). "We have measured the frequency of TGFBR1*6A variants in osteosarcoma cases and controls." (PMID 20429896, 2010). "TGFBR1*6A is a dominant susceptibility allele in the occurrence of osteosarcoma." (PMID 20429896, 2010). "Since tumor cells may exhibit mutations, making their genotypes different from normal tissues, we examined the possibility of loss of homozygosity of TGFBR1 in osteosarcoma tissues in 10 cases with distant metastasis." (PMID 20429896, 2010). "Upregulated TGFBR1 will induce the epithelial-to-mesenchymal transition in osteosarcoma cell lines, which is regulated by the interferon consensus sequence-binding protein, but the specific mechanism is not fully elaborated (ICSBP)." (PMID 32582282, 2020). "Since TGFBR1 is one of the hub genes involved in the regulation mechanism in osteosarcoma affected by matrix mineral, and its differential expression will affect the prognosis and survival of patients." (PMID 32582282, 2020). "However, the relationship between TGFBR1*6A mutation and osteosarcoma occurrence remains unknown." (PMID 20429896, 2010). "The 9A/6A and 6A/6A genotypes of TGFBR1 have a significantly higher frequency in osteosarcoma cases than in controls." (PMID 20429896, 2010). "Analysis of distant metastasis, however, showed that TGFBR1*6A is significantly related with metastasis in osteosarcoma." (PMID 20429896, 2010). "To clarify this relationship, we have analyzed TGFBR1 variation in clinical cases of osteosarcoma and normal controls." (PMID 20429896, 2010).
osteosarcoma (continued). "We found that TGFBR1*6A genotypes are significant associated with osteosarcoma, which lends support to the fact that TGF-β signaling plays a vital role in the occurrence of osteosarcoma." (PMID 20429896, 2010). "TGFBR1*6A positively correlated with the occurrence of osteosarcoma." (PMID 20429896, 2010). "Clarification of the relationship between TGFBR1*6A and osteosarcoma may indicate a role of TGF-β signaling in the etiology of osteosarcoma and provide clues that might help to guide treatment of this diseases." (PMID 20429896, 2010). "However, there are few reports on the function of TGFBR1 in osteosarcoma." (PMID 32582282, 2020). "There have been no reports about the prevalence of TGFBR1*6A mutation in osteosarcoma." (PMID 20429896, 2010). "Although this may not be necessary in determining the occurrence of osteosarcoma, TGFBR1*6A variants appear to increase susceptibility to osteosarcoma." (PMID 20429896, 2010). "Therefore, TGFBR1*6A variants increased the susceptibility of osteosarcoma universally but not specifically to some cases with different gender, age and location of the tumor." (PMID 20429896, 2010). "Furthermore, we demonstrate, through the use of transforming growth factor beta receptor 1 (TGFBR1) inhibitors and CRISPR-Cas9-mediated knockouts, that TGFβ1 present in osteosarcoma cell-derived EVs is responsible for lung fibroblast differentiation." (PMID 32751693, 2020). "This indicates that TGFBR1*6A makes for some functional modification of TGF-β signaling which stimulates the occurrence of osteosarcoma without regard to gender, age and location." (PMID 20429896, 2010).
autoimmune disease (7 papers, 2015 to 2022). A disorder resulting from loss of function or tissue destruction of an organ or multiple organs, arising from humoral or cellular immune responses of the individual to their own tissue constituents. "The identified targets TGFBR1 and IGF1R have been shown to be downregulated in blood cells of patients with autoimmune disease and a loss of SP1 and knockdown of GNAI1 have been described to impair hematopoiesis and immune cell migration capability, respectively." (PMID 31569706, 2019). "The amount of autoimmune diseases in the family was remarkable, but appeared not to be associated with the TGFBR1 mutation, nor with a gene close to chromosome 9q22." (PMID 31475485, 2019). "Among them, TGFBR1, TGFBR2, CCL5, CD48, CD244A, and CD72 have been reported to be closely related to the pathophysiologic processes of autoimmune diseases." (PMID 35515003, 2022).
diabetic nephropathy (7 papers, 2007 to 2025). "In the present study, we aimed to explore the protective effects of NAR on kidney as well as its effects on let-7a/TGFBR1 signaling in diabetic nephropathy rats and mesangial cell under high glucose condition." (PMID 27446963, 2016). "In summary, we investigated if putatively functional variants in three genes, TGFB1, TGFBR1 and TGFBR2, contribute to genetic susceptibility to diabetic nephropathy in type 1 diabetes." (PMID 17319955, 2007). "Variants have been recorded for both TGFBR1 and TGFBR2 genes, however there is limited genomic information regarding their influence on diabetic nephropathy." (PMID 17319955, 2007). "Inhibition of TGFBR1 signaling pathway ameliorated kidney injury in diabetic nephropathy." (PMID 40166052, 2025). "In addition, let-7a upregulation in renal tissue diminished the expression of transforming growth factor-β1 receptor 1 (TGFBR1), required for the regulation of Let-7a/TGFBR1 signaling pathway in diabetic nephropathy." (PMID 33672251, 2021). "Additionally, naringenin might repress glomerular mesangial cells proliferation and ECM accumulation through let-7a/TGFBR1 signaling in DN, and let-7a may be a potential new target for the protection of naringenin against diabetic nephropathy." (PMID 35327559, 2022). "The naringenin might be another effective component and was reported to alleviate acute inflammation by adjusting the degradation by intracellular cytokines and to reduce kidney damage in diabetic nephropathy through Let-7a/transforming growth factor-β1 receptor (TGFBR1) signalling." (PMID 30013616, 2018). "There is considerable evidence supporting the role of TGFB1, TGFBR1 and TGFBR2 genes in the development of diabetic nephropathy." (PMID 17319955, 2007). "The activity of TGFβ1 is facilitated by the action of type 1 and type 2 receptors, with both receptor genes (TGFBR1 and TGFBR2) shown to be upregulated in diabetic kidney disease." (PMID 17319955, 2007). "A report on the diabetic nephropathy suggested that estradiol had an inhibitory effect on TGFBR1, however, there were no significant sex differences with regard to the renal function and fibrosis, consistent with our data." (PMID 36430681, 2022). "Our results suggest common variants in TGFB1, TGFBR1 and TGFBR2 genes do not strongly influence genetic susceptibility to diabetic nephropathy in an Irish Caucasian population." (PMID 17319955, 2007). "Moreover, NAR might repress glomerular mesangial cells proliferation and accumulation of ECM by let-7a/TGFBR1 signaling in DN, and let-7a may be a novel potential target for NAR protecting against diabetic nephropathy." (PMID 27446963, 2016).
oral cancer (7 papers, 2002 to 2022). "Taken together, these data suggest that over-expression of miR-142-3p in oral cancer and dysplasia cells is associated with reduced carcinogenicity in vitro at least partially due to by decreasing TGFBR1 expression." (PMID 28146434, 2017). "A literature search for potential targets of miR-142-3p using PubMed and GeneRIF revealed TGFBR1 as the only candidate that showed interaction with miR-142-3p in epithelial cancers and has also been implicated in oral cancer progression." (PMID 28146434, 2017). "Oral cancer cells containing EVs that have miR-142-3p promote angiogenesis mediated by TGFBR1 (transforming growth factor-beta receptor 1)." (PMID 35159299, 2022). "The same target of miR-142-3p identified in oral cancer cells, TGFBR1, showed a decrease with the addition of miR-142-3p to endothelial cells both via over expression and the addition of SEVs." (PMID 28146434, 2017). "Indeed, a previous study showed that inhibiting the phosphorylation of STAT3 effectively inhibited the expression of PD-L1 in oral cancer cell lines (CAL27 and FaDu) and Tgfbr1/Pten 2cKO, an HNSCC mouse model." (PMID 34063134, 2021). "To elucidate the role of TGFBR3 in TGF-β signaling in oral cancer cells, we determined the effect of TGFBR3 expression on phosphorylation of SMAD2/3, an activation mark of the canonical TGF- β pathway, with or without SB431542, an inhibitor of TGFBR1." (PMID 32471132, 2020).
adenoma (6 papers, 2009 to 2023). A neoplasm arising from the epithelium. "We also examined whether germ-line TGFBR1 mutations are responsible for the CRC susceptibility locus on chromosome 9 by screening the entire coding region of TGFBR1 in affected members of a large family with adenoma and CRC linked to chromosome 9q22.32-31.1." (PMID 19401691, 2009). "These genes were involved in different stages of cancer development as analyzed using the KEGG pathway, this includes SMAD4 and TGFBR1 at the late adenoma, and AKT3 and PIK3R2 at the carcinoma stage in CRC development." (PMID 36499586, 2022). "The results also included previously unreported genes including AKT3, NCOR2, PIK3R2, SMAD4, and TGFBR1, from which AKT3 and PIK3R2 were present in the early adenoma stage and SMAD4 and TGFBR1 were present at the late adenoma stage." (PMID 36499586, 2022). "Mutational analysis of TGFBR1 in the earlier published family 24 with CRC and adenoma linked to chromosome 9q22.32-31.1 showed no sequence changes on the linked haplotype." (PMID 19401691, 2009). "The mutation of the Apc along with TGFβ type 1 receptor (Tgfbr1/Alk5) does not lead to the adenoma formation." (PMID 37124519, 2023).
Aortic dissection (6 papers, 2016 to 2024). Aortic dissection refers to a tear in the intimal layer of the aorta causing a separation between the intima and the medial layers of the aorta. "LDS is caused by an abnormality in transforming growth factor‐β (TGF‐β) signaling pathway‐related genes, and fatal aortic dissection (AD) and rupture often occur at a younger age and with smaller vessel diameters than MFS, particularly in Type 1–3 LDS (TGFBR1/2: LDS1/2; SMAD3: LDS3)." (PMID 39130808, 2024).
asthma (6 papers, 2019 to 2025). "In this modest number of genes identified several have been previously associated with airway biology and disease including e.g. TGFBR1, the receptor for TGFB1 involved in fibrosis and IL6R a cytokine receptor implicated in airway disease e.g. asthma." (PMID 31370853, 2019). "Interestingly, single nucleotide polymorphisms at or near the TGFBR1, SMAD3, and SMAD6 loci are linked to asthma risk, and at least 1 such polymorphism localizes to an open chromatin region in human MCs." (PMID 39744949, 2025). "Importantly, functional validation of GWAS candidate asthma risk genes have uncovered key roles in HRV infection susceptibility (ORMDL3 and CDHR3) and TGFβ signalling (GSDMB, TGFBR1, and SMAD3)." (PMID 32887352, 2020). "Notably, TGFBR1 and SMAD3, which mediate TGFβ signalling, are susceptibility loci identified in GWAS for asthma." (PMID 32887352, 2020).
renal cell carcinoma (6 papers, 2010 to 2023). "The frequency of a G → A mutation located 24 nt downstream of TGFBR1 intron 7 was significantly increased in RCC (renal cell carcinoma) and TCC (transitional cell carcinoma) patients compared to individual controls without cancer." (PMID 37009804, 2023).
skin tumors (6 papers, 2014 to 2021). "A higher proportion of patients (14%) developed skin tumors than would be expected if they had a predisposition to tumor development conferred by variants at the TGFBR1 linked locus that predispose to MSSE." (PMID 33256177, 2020). "Inactivation of both Tgfbr1 alleles significantly increased the number of tumours per mouse and dramatically shortened both skin tumour-free survival (all mice developing skin lesions within 63 days of induction) and overall survival (median survival 51 days)." (PMID 27558455, 2016). "No pathogenic TGFBR1 sequence variants or larger scale deletions or duplications of the TGFBR1 gene were detected in affected members of four families with familial self-healing skin tumors." (PMID 33256177, 2020). "A macroscopic evaluation of the skin of fifteen 12-month-old heterozygous Tgfbr1 mutant mice did not reveal any scars similar to those observed in human MSSE patients after spontaneous regression of the skin tumors." (PMID 33256177, 2020). "A macroscopic evaluation of the skin of fifteen 12-month-old heterozygous Tgfbr1 mice did not reveal any scars as observed in human MSSE patients after spontaneous regression of the skin tumors." (PMID 24587008, 2014).
colorectal tumor (5 papers, 2007 to 2022). "First, we wanted to know if the GCG repeat is a specific target for frameshift mutations in MSI colorectal tumours, and in the event, if somatic acquisition of TGFBR1*6A allele occurs in these MSI tumours, similar to metastatic CRC." (PMID 19538729, 2009). "In addition, there was a much higher frequency of this allele found in colorectal tumor tissue than in germ-line DNA extracted from the same patients, suggesting that acquisition of Tgfbr1-6A allele may be contributed by cancer-associated somatic deletions." (PMID 17705854, 2007). "Despite the majority of CRCs having deactivating TGF‐β pathway mutations (TGFBR1, TGFBR2, SMAD4, SMAD2, SMAD3), colorectal tumours produce significant amounts of TGF‐β, creating a TGF‐β rich environment, to which only the stromal compartment can respond." (PMID 35595718, 2022).
endometriosis (5 papers, 2014 to 2024). The growth of functional endometrial tissue in anatomic sites outside the uterine body. "In our omics results, we observed an elevation in the expression of critical fibrosis-associated proteins, including TGFBR1, α-SMA, CTHRC1, FAP, FN1, and 15 collagen proteins, in endometriosis." (PMID 38735939, 2024). "The results revealed that knockdown of TRIM33 significantly enhanced the protein expression of TGFBR1/p-SMAD2/α-SMA/FN1, suggesting that the reduced levels of TRIM33 protein in ectopic tissues may exacerbate endometriosis-associated fibrosis." (PMID 38735939, 2024). "Consequently, we hypothesize that reduced TRIM33 expression in endometriotic tissues may contribute to the development of endometriosis fibrosis by enhancing TGFBR1/p-SMAD2/α-SMA/FN1 expression." (PMID 38735939, 2024).
keloid (5 papers, 2009 to 2025). An irregularly shaped, elevated mark on the skin caused by deposits of excessive amounts of collagen during wound healing. "In addition, noncoding RNAs such as miR‐29a‐3p, which normally represses COL1A1 and TGFBR1, are downregulated in keloids, whereas competing lncRNAs (e.g., H19) and circRNAs (e.g., hsa_circ_0020792) sequester miRNAs to further activate TGF‐β/Smad signaling and collagen expression." (PMID 41049267, 2025). "ScRNA-seq analysis identified consistent expression patterns for TEM1, ACTA2, COL1A1, FN1, TGFBR1, and TGFBR2 in distinct fibroblast subsets of both keloids and hypertrophic scars." (PMID 38254097, 2024). "In addition, the mRNA expression levels of ECM genes including COL1A1 and FN1 as well as that of TGF-β-related genes such as TGFB1, TGFBR1, and TGFBR2 were highly expressed in keloids." (PMID 38254097, 2024). "Additionally, SNPs in TGFBR1 (e.g., rs334348) increase Smad2/3 phosphorylation and promote fibroblast‐to‐myofibroblast differentiation, a transition widely observed in the hypercontracting and fibrotic phenotypes of fibroblasts isolated from HTS and keloids." (PMID 41049267, 2025).
osteoporosis (5 papers, 2009 to 2023). A condition of reduced bone mass, with decreased cortical thickness and a decrease in the number and size of the trabeculae of cancellous bone (but normal chemical composition), resulting in increased fracture incidence. "For instance, let-7f-5p regulated osteogenesis and bone formation by targeting TGFBR1 to ameliorate osteoporosis." (PMID 37187956, 2023). "Such clustering results are interesting as TGFBR1, TGFBR2 and SMAD3 formed a cluster that showed enhanced expression in primary osteoporosis." (PMID 36443839, 2022).
pulmonary hypertension (5 papers, 2014 to 2025). Increased pressure within the pulmonary circulation due to lung or heart disorder. "Second, TGFBR1 up-regulation has been reported to be related with pulmonary hypertension, and we have indentified that TGFBR1 was a direct target of let-7b." (PMID 24978044, 2014). "In monocrotaline induced pulmonary hypertension rat model, TGFBR1 was highly expressed in the lung." (PMID 24978044, 2014).
chronic kidney disease (4 papers, 2020 to 2025). Impairment of the renal function secondary to chronic kidney damage persisting for three or more months. "Moreover, miR-135a-5p is a key regulator of the TGFBR1/TAK1 pathway, resulting in the attenuation of vascular inflammation in rats with chronic kidney disease." (PMID 34440873, 2021).